TDO2 (tryptophan 2,3-dioxygenase)
Diseases named in the same sentence as TDO2 in open-access papers (continued):
Sharing a sentence is not in itself a finding about the gene and the disease.
infection (12 papers, 2016 to 2025). The state of being infected such as from the introduction of a foreign agent such as serum, vaccine, antigenic substance or organism. "Among the infection-induced genes, ido1 and tdo2 were found, but for robust protein-level induction of IDO1, the addition of IFNG was needed." (PMID 34819931, 2021). "DNA microarray or next-generation sequencing data also showed that IDO2 and TDO2 are up-regulated by infection or immune activation." (PMID 34871367, 2021). "TDO2 protein levels and serum tryptophan to kynurenine ratio were regulated up to 8 days after infection, coinciding with the peak of antiviral T cell responses in the LCMV infection model." (PMID 33045014, 2020). "Similar to Tdo2, the genes Acmsd and Aox1 were significantly upregulated in liver tissue in the innate phase of infection." (PMID 33045014, 2020). "Upon LCMV Cl13 infection, expression of Tdo2 peaked after 2 days and TDO2 protein levels remained significantly elevated up to 8 days after infection." (PMID 33045014, 2020). "Induction of Tdo2 peaked at 1.5 days post infection (dpi), following IFN-I serum kinetics." (PMID 33045014, 2020). "Thus, Tdo2-deficiency did not result in altered serum homeostasis of the tryptophan to kynurenine ratio during infection, which seemed to be independent of hepatocyte-intrinsic compensation via the IDO-axis." (PMID 33045014, 2020). "For example, in tryptophan metabolism, the expression of tryptophan hydroxylase 1 (TPH1, FC = 61) and tryptophan 2,3-dioxygenase (TDO2, FC = 4.2) was upregulated, potentially affecting tryptophan biosynthesis after CH60 infection." (PMID 30197639, 2018). "Infection with the non-hepatotropic LCMV strain Armstrong 53b (LCMV Arm) induced Tdo2 expression in the liver." (PMID 33045014, 2020). "Tdo2–/–and WT mice did not display any differences in viremia in blood, liver, spleen or kidney 2 days after infection." (PMID 33045014, 2020). "Infection with T. gondii activates inflammatory molecules—Interferon gamma (IFN-γ), Interleukin-2 (IL-2), and Tumor necrosis factor alpha (TNF-α)—which upregulate tryptophan-2,3-dioxygenase (TDO) and indoleamine-2,3-dioxygenase (IDO) while leading to degradation of tryptophan into kynurenine." (PMID 40868805, 2025). "However, given that NAD+-consuming enzymes could help fight infection, an alternative explanation for the up-regulation of IDO1/IDO2/TDO2 is to promote NAD+ biosynthesis." (PMID 34871367, 2021). "Mining a single cell RNA-seq (scRNA-seq) dataset (GSE123688) confirmed a significant infection-induced upregulation of Tdo2 in hepatocytes and further confirmed that Ido1 is not expressed whereas Ido2 seems to be very lowly expressed in hepatocytes and not differentially regulated." (PMID 33045014, 2020). "In the context of LS infection, expression of typical hepatocyte markers such as albumin, tryptophan 2,3-dioxygenase, and liver fatty acid binding protein (Lfabp) was not identified in MBA-differentiated JM8.N4 and E14 cells, confirming the lack of characteristic hepatocyte-like features." (PMID 32442532, 2020). "Expression of TDO2 was not altered in primary AECs or MLE12 cells infected with γHV-68 and in fact was slightly repressed following infection." (PMID 33491663, 2021). "In line with our in vitro results and the HCV data, infection of Ifnar1Δ/Δ and Ifnar1+/+ control mice with LCMV Cl13 led to induction of Tdo2 expression in wild type, but not in conditional IFNAR1 knock out mice." (PMID 33045014, 2020). "Interestingly, we found that after infection with Mtb, the expression level of only IDO1 significantly increased in inflammatory macrophages, whereas other tryptophan-degrading enzymes, such as IDO2 and TDO2, did not significantly change." (PMID 39438693, 2024).
adenocarcinoma (2 papers, 2023 to 2025). A common cancer characterized by the presence of malignant glandular cells. "Since both IDO1 and TDO2 can catalyze the conversion of Trp to Kyn, we asked whether IL-1β can also induce TDO2 expression in adenocarcinoma cells." (PMID 37985999, 2023).
CNS tumor (2 papers, 2022 to 2025). "Tryptophan 2,3-dioxygenase (TDO) was overexpressed in all the CNS tumors which were evaluated, suggesting a rapid degradation of TRP to KYN that causes Trp starvation in the tumor microenvironment and, consequently, the inhibition of the lymphocyte proliferation." (PMID 36355137, 2022). "Overexpression of key KP enzymes, including IDO and tryptophan 2,3-dioxygenase (TDO), is frequently observed in CNS tumor cells, such as gliomas, leading to significantly elevated levels of kynurenine." (PMID 40075568, 2025).
disorders of the immune system (2 papers, 2018 to 2019). "With respect to diseases related to disorders of the immune system, such as infectious diseases, chronic inflammation, autoimmunity and cancer, these models have focused on three KP enzymes: IDO, tryptophan 2,3-dioxygenase (TDO) and kynurenine 3-monooxygenase (KMO)." (PMID 31781097, 2019).
neurological disorders (2 papers, 2009 to 2021). "Recent studies have shown that inhibiting the activities of de novo pathway enzymes, such as tryptophan-2,3-dioxygenase (TDO) and kynurenine-3-monooxygenase (KMO), may help alleviate specific neurological disorders." (PMID 34095234, 2021).
digestive system cancer (1 paper, 2025). A primary or metastatic malignant neoplasm involving any part of the digestive system. "Dysregulation of TDO2 expression has been found in various digestive system diseases, including digestive system cancers and inflammatory digestive system diseases." (PMID 40136551, 2025).
digestive system diseases (1 paper, 2025). "Aberrant expression of TDO2 has been implicated in various digestive system diseases, yet the precise mechanisms underlying its role remain to be fully elucidated." (PMID 40136551, 2025). "Dysregulation of TDO2 expression has been observed in various digestive system diseases, encompassing those related to the oral cavity, esophagus, liver, stomach, pancreas, and colon and rectum." (PMID 40136551, 2025). "This review elucidates the mechanisms by which TDO2 functions within the tryptophan metabolic pathway, its role in digestive system diseases, and recent advancements in TDO2 inhibitor research." (PMID 40136551, 2025).
infectious disease (1 paper, 2020). A disorder directly resulting from the presence and activity of a microbial, viral, or parasitic agent in humans. "The existence of compensatory mechanisms for the loss of Tdo2 suggests a critical role for circulating tryptophan and kynurenine during infectious diseases and beyond." (PMID 33045014, 2020).
neurodevelopmental disorder (1 paper, 2022). A behavioral and cognitive disorder with onset during the developmental period that involves impaired or aberrant development of intellectual, motor, or social functions. "Instead, we identified several rare, likely pathogenic variants in seven genes implicated in neurodevelopmental disorders: KLHL17, TDO2, TRRAP, EIF3F, ATP10A, DICER1, and CDH15." (PMID 35743796, 2022).
TDO2 also shares sentences with these, for which no sentence is quoted: renal cell carcinoma (3 papers); brain tumor (2); cardiovascular disease (2); pancreatic adenocarcinoma (2); skin melanoma (2); Tourette syndrome (2); acute myeloid leukemia (1); AIDS (1); alcohol abuse (1); alcoholic hepatitis (1); Arthritis (1); basal cell carcinoma (1); Breast Invasive Carcinoma (1); carcinoma in situ (1); cholangiocarcinoma (1); chronic kidney disease (1); clear cell renal carcinoma (1); COVID-19 (1); dementia (1); dyslipidemia (1); dysphoria (1); dysplasia (1); gastric tumors (1); Granuloma (1); Hallucinations (1); head and neck squamous cell carcinoma (1); Hypoglycemia (1); inflammation (1); insomnia (1); invasive carcinoma (1).
A further 17 diseases each share a sentence with TDO2 in 1 paper.